SOCS3 (suppressor of cytokine signaling 3)
Diseases named in the same sentence as SOCS3 in open-access papers (continued):
Sharing a sentence is not in itself a finding about the gene and the disease.
autoimmune disease (18 papers, 2014 to 2025). A disorder resulting from loss of function or tissue destruction of an organ or multiple organs, arising from humoral or cellular immune responses of the individual to their own tissue constituents. "Furthermore, unbridled activation of the JAK/STAT signaling pathways due to defective expression or silencing of suppressors of cytokine signaling 1 (SOCS1) or SOCS3 gene is also implicated in pathogenesis of a number of autoimmune diseases." (PMID 27703302, 2016). "Notably, Socs3 supports differentiation of the Th17 and is implicated in autoimmune disease and a recent study reported that the expression of Th17 cell-mediated factors such as ROR-γt, and Stat3 increased significantly in diclofenac-treated mouse liver." (PMID 26934552, 2016). "SOCS1 and SOCS3 have been reported to be aberrantly expressed in some autoimmune diseases and involved in regulating the functions of diverse immune cells." (PMID 34616359, 2021). "SOCS3 plays an essential role in modulating the outcomes of infections and autoimmune diseases by binding to both JAK kinase and cytokine receptors." (PMID 34221740, 2021). "SOCS3 has been reported involving in the progress of various diseases such as autoimmune diseases, cardiovascular diseases, metabolic diseases and tumours, which is responsive to an increase in IL-6 and plays a negative regulatory role in cytokine signalling." (PMID 32272865, 2020). "SOCS proteins, especially SOCS1 and SOCS3, are often dysregulated in a wide variety of autoimmune diseases." (PMID 28418931, 2017). "There is significant interest in developing strategies to efficiently deliver exogenous SOCS1 or SOCS3 into cells as potential therapeutic approach for the treatment of autoimmune diseases." (PMID 27703302, 2016). "In this review, we describe the role of suppressor of cytokine signaling-3 (SOCS3) in modulating the outcome of infections and autoimmune diseases as well as the underlying mechanisms." (PMID 24600449, 2014). "SOCS3 has also been shown to act on a common autoimmune disease, rheumatoid arthritis." (PMID 39676878, 2024). "Studies have revealed aberrant SOCS1 and SOCS3 expressions in diverse autoimmune diseases." (PMID 34616359, 2021). "In the present study, we hypothesized that increases in IL-27 and SOCS3 and a decrease in IL-17A in T. gondii–infected mouse brains would inhibit the progression of autoimmune diseases like EAE." (PMID 33205383, 2021). "Therefore, further studies are needed to determine a potential therapeutic role for AESIS-1 in the upregulation of SOCS3 expression in other autoimmune diseases, such as psoriasis." (PMID 31936141, 2020). "Multiple sclerosis and systemic lupus erythematosus are distinct autoimmune disease, but show certain similarities, including increased STAT3 expression and activation or increased SOCS3 expression." (PMID 33271810, 2020). "The pathogenic mechanisms of autoimmune diseases are complex, and SOCS proteins, particularly SOCS1, SOCS2, SOCS3, and SOCS5, regulate cytokine receptor signaling through distinct mechanisms, thereby participating in the development and progression of autoimmune diseases." (PMID 40755762, 2025). "In addition, MSCs suppress Th17 cell differentiation through IFN-γ-mediated STAT1 activation, which upregulates SOCS3 and inhibits STAT3 signaling, ultimately exerting immunomodulatory effects in autoimmune diseases, including psoriasis." (PMID 40906403, 2025). "Our results suggest that the increase in SOCS3 might have a role in the inactivation of STAT3 to suppress Th17 cell differentiation, aggravating autoimmune diseases such as EAE." (PMID 33205383, 2021). "The SOCS3 protein can trigger a negative feedback process for overactivated cytokine signaling, which is thought to induce autoimmune diseases." (PMID 28418931, 2017).
autoimmune disease (continued). "However, this review has several limitations: current research on the SOCS family and autoimmune diseases predominantly focuses on SOCS1 and SOCS3, with insufficient comprehensive discussion regarding the specific roles of each component within the molecular structure of SOCS proteins." (PMID 40755762, 2025). "Further analysis indicated that SOCS3 promotes the expansion of Th17/IFN-γ CD4 T cell populations, implicating SOCS3 in the progression of severe uveitis and framing it as a potential target for medicinal chemistry campaigns targeting uveitis and other autoimmune diseases." (PMID 39676878, 2024).
Hepatic steatosis (18 papers, 2012 to 2025). Steatosis is a term used to denote lipid accumulation within hepatocytes. "This limitation determines the need for future studies incorporating both functional assays and metabolic analyses to provide a more comprehensive understanding of the mechanisms underlying SOCS3-related lipid accumulation and BBP-induced fatty liver." (PMID 39851554, 2025). "Inhibition of SOCS3 ameliorates hepatic steatosis and hypertriglyceridemia, while knockout of it in liver enhances lipogenesis in obesogenic milieu in mice as there was increased hypothalamic SOCS3." (PMID 32158492, 2020). "Ascorbate ameliorates hepatic steatosis and improves insulin sensitivity through inhibiting lipogenesis and SOCS3." (PMID 32158492, 2020). "SOCS3 is a repressor of insulin signaling pathway and it has been reported that inhibition of SOCS3 ameliorated hepatic steatosis and hypertriglyceridemia." (PMID 32158492, 2020). "In summary, we find a novel insight that ascorbate prevents hepatic steatosis by inhibiting SOCS3 and improving insulin sensitivity in vitro and in vivo." (PMID 32158492, 2020). "Our previous studies have demonstrated that the ERK, PI3K-Akt, and Socs3-Stat3 pathways are involved in the Gab2 regulatory network in fatty liver pathogenesis." (PMID 28842424, 2017). "Our previous study demonstrated that Gab2 recruited PI3K/Akt, suppressor of cytokine signaling 3 (Socs3)/Stat3, and other signaling molecules in fatty liver induced by pathologic factors." (PMID 28842424, 2017). "Expression of SOCS3 has been shown to play a central role in hepatic steatosis and insulin resistance in mice." (PMID 25658428, 2015). "Reduced hepatic fat accumulation found in myriocin-treated DIO mice implicates downregulation of SOCS-3, a gene involved in development of hepatic steatosis." (PMID 23761785, 2013). "Furthermore, elevated leptin levels have been linked to the worsening of hepatic steatosis, as leptin activates the JAK2/STAT3 pathway, increasing the expression of the suppressor of SOCS3, which contributes to hepatic lipid accumulation." (PMID 40862455, 2025). "We found that ascorbate ameliorated hepatic steatosis induced by excess saturated fatty acid influx through changing cellular lipid profiles as well as improving insulin sensitivity which was related to inhibition of SOCS3." (PMID 32158492, 2020). "Here we showed ascorbate partially inhibited SOCS3 expression and ameliorated hepatic steatosis." (PMID 32158492, 2020). "None of the candidate genes that we identified are known to regulate Xbp1s or Socs3, nor have they previously been associated with the pathogenesis of fatty liver." (PMID 25617409, 2015). "Therefore, both human and murine studies demonstrate that hepatic XBP1s and SOCS3 expression are important in the pathogenesis of fatty liver diseases." (PMID 25617409, 2015). "Therefore, regulation of SOCS-3 by ceramide biosynthesis contributes to the pathophysiology of hepatic steatosis." (PMID 23761785, 2013). "Additionally, SOCS3 is closely related to IR development, as its overexpression in the liver leads to IR, while its inhibition enhances insulin sensitivity and ameliorates hepatic steatosis." (PMID 40520339, 2025). "Curcumin inhibits the expression of SREBP1c and the suppressor of cytokine signaling 3 (SOCS-3), and it increases the phosphorylation of the hepatic activator of transcription 3 (STAT3), preventing liver steatosis." (PMID 39061866, 2024). "Furthermore, curcumin has been shown to prevent hepatic steatosis by promoting the phosphorylation of hepatic activator of transcription 3 (STAT3) and by suppressing the expression of SREBP1c and suppressor of cytokine signaling 3 (SOCS-3)." (PMID 37570615, 2023). "In addition, negative inflammatory mediators such as SOCS1 and SOCS3 contribute to hepatic steatosis, inflammation, and fatty necrosis." (PMID 30365523, 2018).
Hepatic steatosis (continued). "Together, these data confirm that both lowered insulin and leptin sensitivity occurred during the development of hepatic steatosis upon HFHS dieting, and suggest that the impairment in hepatic PI3K/Akt pathway may occur earlier than that in hepatic STAT3/SOCS3 pathway." (PMID 25658428, 2015). "After determining that both hepatic Xbp1s and Socs3 mRNA expression was differentially expressed in HFHC diet-fed A/J and C57BL/6 mice, we applied eQTL analysis to identify genetic loci that may be important in the regulation of these genes that influence the pathogenesis of fatty liver disease." (PMID 25617409, 2015).
ovarian carcinoma (18 papers, 2016 to 2025). A malignant neoplasm originating from the surface ovarian epithelium. "Here, we show epithelial ovarian cancer (EOC)-derived exosomes activated macrophages to a tumor-associated macrophage (TAM)-like phenotype with SOCS3/STAT3 pathway involvement, which could facilitate the progression of cancer." (PMID 27172798, 2016). "In the ID8 ovarian cancer mouse model, tumor cells led to overexpression of suppressor of cytokine signaling 3 (SOCS3) in DCs and lowered the activity of the corresponding pyruvate kinase (a crucial enzyme for glycolysis), which inhibited the function of DCs." (PMID 36311734, 2022). "Another research has shown that NR1D1 inhibits activation of the JAK/STAT3 signaling pathway by upregulating the expression of SOCS3, thus suppressing ovarian cancer cell growth and inducing apoptosis." (PMID 35481240, 2022). "Whereas, SOCS3 silencing abolished the function of NR1D1 over-expression on ovarian cancer growth and JAK/STAT3 signaling pathway." (PMID 34330232, 2021). "Our study revealed that NR1D1 inhibited the activation of JAK/STAT3 signaling pathway through up-regulating SOCS3, thus suppressing proliferation and inducing apoptosis of ovarian cancer cells." (PMID 34330232, 2021). "Herein, we explored the function of NR1D1 on the growth of ovarian cancer cells and the activation of SOCS3/JAK/STAT3 signaling pathway." (PMID 34330232, 2021). "The level of SOCS3 in ovarian cancer cell lines was lower than that in NOEC, at both mRNA level and protein level." (PMID 34330232, 2021). "Our work revealed that SPTBN1 suppresses the growth and metastasis of epithelial ovarian cancer via SOCS3-mediated blockade of the JAK/STAT3 signaling pathway." (PMID 32516133, 2020). "Our results suggest that SPTBN1 suppresses the progression of epithelial ovarian cancer via SOCS3-mediated blockade of the JAK/STAT3 signaling pathway." (PMID 32516133, 2020). "Our data indicated that SPTBN1 inhibited cell viability and migration in epithelial ovarian cancer by inhibiting the JAK/STAT signaling pathway through regulation of SOCS3." (PMID 32516133, 2020). "In contrast, miR-221 inhibits tumor progression in diseases such as pancreatic and ovarian cancers, by targeting factors, such as SOCS3 and ADP-ribosylation factor-4 (ARF4)." (PMID 31470827, 2019). "Ginsenoside Rb1, from P. notoginseng, has been reported to decrease the levels of p-STAT3 and SOCS3 in ovarian cancer cells, microglial cells, and obese mice." (PMID 29318137, 2017). "In summary, our data suggest ovarian cancer cells can transfer miR-222-3p to macrophages via exosomes, modulating the phenotype of TAMs by targeting the SOCS3 with involvement in the STAT3 pathway." (PMID 27172798, 2016). "Interestingly, the level of SOCS3 was positively correlated to NR1D1 in ovarian cancer according to data from GEPIA." (PMID 34330232, 2021). "As SOCS3 has a low expression level in ovarian cancer tissues and positively correlated with the level of NR1D1, we speculate that NR1D1 may influence the JAK/STAT3 signaling pathway as well as ovarian cancer cell growth through modulating SOCS3." (PMID 34330232, 2021). "It should be investigated whether SPTBN1-regulated SOCS3 is involved in inflammation and radioresistance during ovarian cancer progression in future studies." (PMID 32516133, 2020). "While MOB1A and CCDC6 were significantly over-expressed in ovarian cancer samples, expression of these genes, as well as of TUBB, PRKAR1A, and SOCS3 appeared to be expressed at high levels in multiple healthy tissue sites." (PMID 36943460, 2023). "It was indicated that silencing SOCS3 abolished the function of NR1D1 over-expression on the proliferation and apoptosis of ovarian cancer cells as well as the activation of STAT3 signal." (PMID 34330232, 2021).
ovarian carcinoma (continued). "A recent study indicated that βII spectrin mediates the inhibition of JAK/STAT signaling pathway through suppressor of cytokine signaling 3 (SOCS3), thereby inhibiting cell growth and migration in epithelial ovarian cancer." (PMID 33390831, 2021). "However, whether SOCS3/JAK/STAT3 is implicated in the role of NR1D1 in ovarian cancer remains not yet clear." (PMID 34330232, 2021). "NR1D1 up-regulated the expression of SOCS3, resulting in suppression of the JAK/STAT3 signaling pathway, thus retarding the growth of ovarian cancer cells." (PMID 34330232, 2021). "In conclusion, our study demonstrated that suppression of SPTBN1 promoted cell growth and migration in epithelial ovarian cancer by activating JAK/STAT signaling pathways, which are blocked by SOCS3." (PMID 32516133, 2020). "Additionally, silencing SOCS3 abolished the effect of NR1D1 over-expression on the proliferation and apoptosis of ovarian cancer cells, confirming that NR1D1 performs its role in ovarian cancer cells through modulating the expression of SOCS3." (PMID 34330232, 2021).
colitis (17 papers, 2015 to 2025). Inflammation of the colon. "Rather, Socs3-deficient neutrophils are critical for the exacerbation of DSS-induced colitis in Socs3ΔLysM mice." (PMID 37283760, 2023). "Our study revealed an increase in Il1β expression by Socs3-deficient neutrophils at the RNA level during DSS-induced colitis." (PMID 37283760, 2023). "Future studies will determine the role of increased anti-microbial peptides in Socs3-deficient neutrophils in colitis." (PMID 37283760, 2023). "Our results indicate that Socs3 deficiency in myeloid cells leads to more severe colitis induced by DSS, which correlates with increased infiltration of monocytes and neutrophils in the colon and increased numbers of monocytes and neutrophils in the spleen." (PMID 37283760, 2023). "Depletion of neutrophils using a neutralizing antibody to Ly6G significantly improved the disease severity of DSS-induced colitis in Socs3-deficient mice." (PMID 37283760, 2023). "In mice models of colitis associated cancer, SOCS3 deletion in intestinal epithelial cells (IEC) exacerbated the development of cancer through constitutive STAT3 activation leading to IEC proliferation." (PMID 34604264, 2021). "In contrast, decreased SOCS3 expression and methylation of SOCS3 were observed in patients with colitis-associated CRC." (PMID 28852270, 2017). "Thus, our results suggest that deficiency of Socs3 in myeloid cells exacerbates DSS-induced colitis and that Socs3 prevents overt activation of the immune system in IBD." (PMID 37283760, 2023). "Furthermore, our results demonstrate that the expression of genes related to the pathogenesis and diagnosis of colitis such as Il1β, Lcn2, S100a8 and S100a9 were specifically enhanced in Socs3-deficient neutrophils localized to the colon and spleen." (PMID 37283760, 2023). "Furthermore, depleting Socs3-deficient neutrophils using a monoclonal neutralizing antibody significantly improved the pathology of colitis in mice." (PMID 37283760, 2023). "Furthermore, downregulation of SOCS3 was also observed in patients where colitis resulted in carcinogenesis, suggesting that loss of inhibition on STAT3 promotes the development of cancer during colitis." (PMID 34604264, 2021). "These molecular mechanisms collectively underlie SOCS3’s demonstrated capacity to ameliorate inflammatory processes and restore epithelial integrity in experimental models of DSS-induced colitis." (PMID 40506039, 2025). "As such, further study is required to elucidate the role of the STAT3/SOCS3 axis in myeloid cells to understand their role in the pathogenesis of colitis." (PMID 37283760, 2023). "In the present study, we report the detrimental role of myeloid cell Socs3 deletion in DSS-induced colitis." (PMID 37283760, 2023). "Meanwhile, it has been suggested that IL-22 exhibited protective ability in regulation of gut inflammation by stimulating colon epithelial cell lines to produce IL-10 and SOCS3 to ameliorate DSS-induced colitis via upregulating claudin-2 expression." (PMID 36092152, 2022). "SOCS3 is an important member of this family, being expressed in intestinal epithelial cells and lamina propria in both mouse colitis models and patients with UC, thus playing an important role in the pathogenesis of colitis." (PMID 34211567, 2021). "Compared with the sham group, the levels of p-JAK2, p-STAT3, and SOCS3 significantly increased in the colitis group." (PMID 34594215, 2021). "The expression of miR-19b in TNBS-induced colitis was decreased, while the expression of SOCS3 in TNBS-induced colitis was increased compared with the control." (PMID 25997679, 2015). "Thus far, our results have suggested a strong correlation between Socs3 deletion, augmented neutrophil infiltration, increased expression of pro-inflammatory mediators by neutrophils, and exacerbated colitis." (PMID 37283760, 2023). "Moreover, gastric administration of arbutin considerably reversed the expression changes of p-JAK2, p-STAT3, and SOCS3 in colitis." (PMID 34594215, 2021).